SDHB (succinate dehydrogenase complex iron sulfur subunit B)
Diseases named in the same sentence as SDHB in open-access papers (continued):
Sharing a sentence is not in itself a finding about the gene and the disease.
tumor (continued). "A little more than half of tumors with the SDHD:p.H102R variant showed negative or weak diffuse staining of the SDHB subunits regardless of the sex of the patient or tumor localization." (PMID 36614070, 2022). "Immunohistochemically, tumor cells in SDHB-, SDHC-, and SDHD-deficient RCC are negative for SDHB but positive for SDHA." (PMID 35869040, 2022). "Hypermethylation was higher in SDHB-mutated PPGL when compared to SDHA, SDHC and SDHD cases, which may explain the greater metastatic potential of SDHB-mutated tumours." (PMID 35938916, 2022). "An sdhb-KO model developed in zebrafish recapitulates typical phenomena related to loss of SDHB but appears to show no biology relevant to tumour development in humans." (PMID 36178902, 2022). "According to the results of the experimental validation of the samples, three genes (SDHB, ULK1, and CCS) had the highest risk scores and the same trend of the gene expression between tumor and normal tissues when compared with DEGs in TCGA, which means that our model has consolidated verification." (PMID 36505872, 2022). "This is concordant with the overlap in the CIMP hypermethylation pattern between the kidney tissue derived HLRCC and SDHB-RCC tumors and the degree of variation observed between the different tumor types (RCC, GIST, and Pheo/PGL) associated with germline SDHB mutation." (PMID 36455002, 2022). "Interestingly, we found that proliferation of MTT tumour cells (either wt or SDHB sil) was significantly decreased already after two days of treatment with 4 and 8 mM of metformin, as compared to their untreated counterparts." (PMID 35884532, 2022). "NEO cells were confirmed by inference of aneuploidy (InferCNV), showing chromosomal loss profiles concordant with SNP-array data (where available) and loss of heterozygosity for PCPG tumor-suppressor driver genes including VHL (chr3p), NF1 (chr17q), TMEM127 (chr2q) and SDHB (chr1p)." (PMID 36271074, 2022). "In one patient (143tc), we observed a heterogeneous SDHB expression pattern presented as regions with positive and negative SDHB IHC staining, which can be caused by different cell population within the tumor." (PMID 36614070, 2022). "The patient with the nonsense variant in the SDHB gene was diagnosed at age 54 years with a metastatic secreting-PGL tumor, with neither a personal history of second primary tumors nor a family history of PGL/PCC tumors." (PMID 36685941, 2022). "The low expression of SDHB in ccRCC tissues also suggested that SDHB might be a tumor suppressor in ccRCC." (PMID 34094922, 2021). "In addition to the significant ROS production, SDHB-silenced tumor cell lines (MPC and human pheochromocytoma precursor cells; hPheo1) accumulate iron, whereby treatment with ascorbic acid disrupts redox hemostasis, leading to ROS overload." (PMID 34359671, 2021). "Notably, the RET-mutant effect required the presence of dexamethasone while the SDHB-mutant effect required its absence, providing a plausible explanation for the tumor location preference." (PMID 33947839, 2021). "Besides, the tumor cells lack SDHB expression, but normal intestinal mucosa and vascular elements were positive which verify adequate immunohistochemical detection." (PMID 33612108, 2021). "On the other hand, SDHB-mutated cells proliferate in extra-adrenal to form tumors by virtue of downregulating GIPC2, while in the adrenal the proliferation is countered by glucocorticoid-induced GIPC2 and tumor seldom forms." (PMID 33947839, 2021). "We used cell experiments to verify the tumor-suppressive effect of SDHB on ccRCC." (PMID 34094922, 2021). "Tumor metabolomics and detailed immunohistochemistry of SDHB, FH and GLS1 enzymes may provide help in the future." (PMID 34439371, 2021). "Interestingly, in about 6% of PHTS patients, some germline variants in genes that encode subunits of mitochondrial complex II such as SDHB, SDHC, and SDHD (SDHx) can act as modifiers of PTEN-associated cancer risk and tumor histology." (PMID 33495912, 2021).
tumor (continued). "Additionally, the expression of SUCNR1, HIF-1α, succinate dehydrogenase (SDH) A, and SDHB was higher in the tumor tissue than in the matched normal mucosa." (PMID 33916314, 2021). "However, while tumours with mutations in VHL are generally benign, those with SDHB mutations have an infamously high metastatic potential." (PMID 33138083, 2020). "For a subset of the cancer predisposition genes, such as SDHA and SDHB (encoding for mitochondrial enzymes), none of the tumours showed chromothripsis, despite a secondary somatic hit in all cases (n = 5)." (PMID 32385320, 2020). "The predominance of samples with an invasion lacking SDHB immunoreactivity agrees with several human studies, which show that a lack of SDHB immunoreactivity is associated with more aggressive tumor behavior." (PMID 32957698, 2020). "Second, we found loss of SDHB expression in tumor tissues of PGLs and GIST from variant carriers but not in normal tissue, suggesting the dysfunction of the SDH enzyme." (PMID 33031286, 2020). "Both high and low SDHB staining scores were observed in the sporadic tumor group." (PMID 32150977, 2020). "Glutaminase-1 and SDHB expressions were tested in 35 Pheo/PGL tumor tissues." (PMID 32150977, 2020). "Additionally, SDHB low expression levels in patients with HCC induced a metabolic shift from aerobic respiration to glycolysis and were associated with advanced tumor stage and poor survival rate." (PMID 31881713, 2019). "The cytoplasm of the tumor cells was voluminous, flocculent eosinophilic, and vacuolated mimicking SDHB-deficient RCC and with small nuclei without nucleoli (WHO/ISUP grade 1)." (PMID 31828108, 2019). "The SDH subunit B (SDHB) being one of the four subunits of SDH and the essential one for electron transport is regarded as tumor suppressor because its mutational inactivation or its decreased expression has been observed in several tumor entities." (PMID 31877753, 2019). "Since CP represents one major risk factor for PDAC development, it was investigated whether a chronically inflamed microenvironment alters gene expression of SDHB, a metabolic key protein and described tumor suppressor, in pancreatic ducts." (PMID 31877753, 2019). "Furthermore, “disease modifying genes” have been recognized, including somatic mutations in ATRX, which mostly co-exist with mutations in SDHB or IDH1/2, with a suggested synergistic effect on tumorigenesis and tumor progression." (PMID 31362359, 2019). "Immunohistochemistry for SDHB disclosed diffuse intense granular staining in cytoplasm of non-neoplastic cells and a less intense but definite diffuse granular cytoplasmic positivity (mitochondrial pattern) in tumor cells." (PMID 31092265, 2019). "Therefore, it is important to use an internal positive control in non-neoplastic cells, such as endothelial, stromal, or inflammatory cells, throughout the tumor before interpreting SDHB immunohistochemistry." (PMID 30971719, 2019). "Although the SDHx-associated tumor spectrum is expanding, none of these malignancies have been directly linked to SDHB or SDHD variants." (PMID 30658386, 2019). "In this study, knockdown of SDHB expression in human HCC cells was associated with a shift in the cellular biogenetics from aerobic respiration to glycolytic metabolism and a simultaneous increase in tumor malignancy." (PMID 29449614, 2018). "Immunohistochemistry to SDHA and SDHB in the tumor sample may also provide useful information to prioritize the genetic screenings." (PMID 29755524, 2018). "Moreover, a SDHB-knockdown cells-transplanted xenograft mouse model also displayed a larger tumor volume than that in mice transplanted with mock or vector-transfected cells." (PMID 29449614, 2018). "To determine whether SDHB plays a pivotal role during tumor progression and malignancy, we evaluated the effect of SDHB inhibition using RNAi on HCC Hep3B cells." (PMID 29449614, 2018).
tumor (continued). "In addition, the preliminary analysis showed that most of the HCC tumor specimens exhibited low to moderate levels of SDHB expression, suggesting that SDHB expression is altered during hepatic carcinogenesis or tumor progression." (PMID 29449614, 2018). "Furthermore, the univariate analyses showed that SDHB low expression, alpha-fetoprotein (AFP), tumor capsule, tumor size, tumor grades and pathological stages were associated with both disease-free and overall survival." (PMID 29449614, 2018). "As the risk to SDHB‐linked patients is not confined to one specific anatomical region or tumour type, these decisions are probably made most appropriately by a dedicated multidisciplinary team." (PMID 29951630, 2018). "Patients screened for low SDHB expression in tumor tissues and who have a poor prognosis may be treated with anticancer drugs that specifically target the Warburg effect." (PMID 29449614, 2018). "Interestingly, proband 2 had evidence of succinate dehydrogenase deficiency on SDHB immunostaining of the PC, but immunostaining showed preserved SDHB expression in the RCC tumor." (PMID 28973655, 2017). "Loss of SDHB immunostaining in the PC from case 2 prompted additional sequencing of tumor tissue from the PC and RCC because germline testing did not reveal a germline mutation in SDHx or VHL." (PMID 28973655, 2017). "The p.Cys68Tyr variant has previously been described in patients with PCC or PGL, where IHC analysis of tumor tissue showed no SDHB staining or LOH of the wild-type SDHB allele." (PMID 27279923, 2016). "The viable areas located at the periphery of the tumor contained numerous cells undergoing pyknosis, and the cytoplasm of these tumor cells was immunohistochemically positive for synaptophysin, tyrosine hydroxylase, and chromogranin A. The tumor cell nuclei were positive for SDHB." (PMID 27729064, 2016). "Overexpression of the miRNA cluster 182/96/183 is specific in SDHB-mutated tumours and induces malignant traits, whereas silencing of the imprinted DLK1-MEG3 miRNA cluster appears as a potential driver in a subgroup of sporadic tumours." (PMID 25625332, 2015). "As tumours contain immune cells and can have hypoxic regions, we hypothesized that some degree of SDHB c.136C>U variation may be noticeable in the RNA sequences of the TCGA samples." (PMID 25898173, 2015). "In particular, patient 5 was interesting in whom the germline mutation was a large deletion affecting exons 6–8 of the SDHB gene, whereas in the tumor sample the whole gene was deleted with no detectable exons 6–8 and a reduced amount of the other exons." (PMID 25494863, 2015). "In fact, defect in SDHB induces tumor formation due to succinate accumulation." (PMID 25419056, 2014). "SQ showed high expression for Glut-1 in tumor, AD for SDHB in stroma and PD for CAIX in stroma." (PMID 24387319, 2014). "Loss of heterozygosity (LOH) was observed in 1/1 SDHB, 11/11 VHL and 3/3 NF1-associated tumours." (PMID 24466223, 2014). "The Glutamate--cysteine ligase catalytic subunit (GCLC), the only protein annotated with the term sulfur amino acid metabolism process, had increased abundance while succinate dehydrogenase [ubiquinone] iron-sulfur subunit, mitochondrial precursor (SDHB), a tumor suppressor, had decreased abundance." (PMID 25419056, 2014). "In analysis of correlation between metabolism-related protein expression in tumor and stroma, there was a significant correlation in SDHB (T) and SDHB (S) (r = 0.309, p = 0.006), SDHB (T) and SDHA (S) (r = 0.290, p = 0.011), and SDHB (T) and ATP synthase (S) (r = 0.235, p = 0.039)." (PMID 24387319, 2014). "Using immunohistochemistry, we confirmed our recently described observation that SDHB protein expression was completely lost in tumor cells of SDH-related patients and noticeably reduced in VHL-tumors, while it was still present in vascular endothelial and smooth muscle cells." (PMID 19763184, 2009).
tumor (continued). "Additionally, positive SDHB expression is inversely correlated with tumor biological characteristics, such as the Ki-67 cell proliferation index, suggesting that SDHB plays a crucial role in regulating tumor biological behavior." (PMID 41333221, 2025). "Notably, CD36 protein levels were downregulated after SDHB was overexpressed in both cell lines, which is in line with the finding that CD36 protein levels were higher in tumor samples from patients with SDH-deficient GISTs than in those from patients with SDH-competent GISTs." (PMID 41184234, 2025). "The tumor also showed preserved SDHB expression, suggesting the absence of an SDHB mutation." (PMID 40909300, 2025). "When SDHB IHC is absent, a tumor is considered SDH‐deficient GIST." (PMID 39927693, 2025). "Finally, genetic testing revealed that succinate dehydrogenase complex iron sulfur subunit B (SDHB) heterozygous frameshift mutation in the exon 3/8 (c.237del, p.Lys80ArgfsTer8) was the possible pathogenic mutation sites related to tumor genetic susceptibility." (PMID 38439039, 2024). "Higher gene expression of SDHB may provide more energy for tumor cells in WT." (PMID 38678251, 2024). "Thus, the variables selected for the multivariable analysis were central or confluent necrosis, mitotic index more than 3 mitoses/10 HPF, high cellularity, tumor size of 8.1 cm or greater, PGLexAd, presence of PV in the SDHB gene, and extension to adipose tissue." (PMID 38799767, 2024). "While the current model does not allow for investigating tumour initiation and development, it is a unique model representing the human carrier situation genetically and metabolically, enabling research into risk factors associated with SDHB heterozygosity." (PMID 39000369, 2024). "In addition, 1 patient with PDGFRA D842V mutation got 8.5 months PFS and no tumor progression happened and 3 patients with SDHB-deficient GIST had average of 16 months PFS." (PMID 36779523, 2023). "Indeed, in SDHB mutant cells, altered metabolites may lead to different anti-tumor vs. pro-tumor responses, which overcomes the defect of SDHB dysfunction in cell growth and development." (PMID 37840772, 2023). "A recent study on the tumor immune microenvironment of PPGLs is consistent with this notion since the lowest proportion of cytotoxic T-lymphocytes in PPGLs has been associated with SDHB mutations." (PMID 36439433, 2022). "In the present study, the tumor cells of SDHB-deficient tumors with SDHB gene mutation showed higher expression of Nrf2 than the tumors without this mutation, indicating that a sustained activation of Nrf2 has a role in tumorigenesis of PCC/PGL with SDHB gene mutations." (PMID 35300626, 2022). "Also, HLRCC tumors may either create more fumarate or retain a higher concentration of fumarate within the tumor cells that the SDHB-RCC tumors can for succinate." (PMID 36455002, 2022). "SDHA was expressed in all tumor cells, regardless of whether the cells were positive or negative for SDHB gene mutations." (PMID 35300626, 2022). "TS-Hyper probes were identified for the SDHB-RCC tumors in this cohort and the two external cohorts (Pheo/PGL and GIST) by selecting probes with β-values of ≤0.2 in all normal tissue associated with each cohort and an average tumor β-value ≥0.4 higher than the average normal tissue β-value." (PMID 36455002, 2022). "However, for animals bearing MPC SDHBWT liver metastasis, brusatol did not effectively suppressed tumor growth, as on the SDHB-deficient cells." (PMID 31979226, 2020).
tumor (continued). "In contrast to the SDHB-knockdown cells, cells with SDHB overexpression indeed exhibited a slight change in cell morphology and a clear decrease of both cell growth and migration, suggesting that the SDHB could act as a tumor suppressor." (PMID 29449614, 2018). "Therefore, we can suggest that patient has non-highly pathogenic mutations in both copies of SDHB or in the same copy that caused cumulative effect and became the reason for tumor growth." (PMID 29504908, 2018). "Immunohistochemical staining of the resected tissue may also suggest the presence of an SDHB/SDHD mutation; as tumours affected by these mutations will have negative staining for SDHB antibodies; this can be used to guide and streamline testing." (PMID 28965289, 2017). "Low or negative SDHB expression in the tumor was associated with higher T stage (P = 0.011)." (PMID 23888270, 2013). "The sensitivity of this technique in malignant PGLs may be lower as evidenced in situation highly associated with malignancy as in SDHB mutation carriers (see later) or patients with dopamine-secreting tumours which usually do not uptake MIBG." (PMID 22851969, 2012). "Although elevated levels of Cu2+ are found in multiple tumor tissues and serum, key cuproptosis genes, includingFDX1,SDHB,DLAT, andDLST, are downregulated in tumor tissues." (PMID 40692442, 2025). "Together, these results indicate that pseudohypoxia is activated under normoxic conditions in the R244H point mutant SDHB model due to succinate accumulation, just like in PPGL tumor cells." (PMID 41155475, 2025). "Immunohistochemistry showed that the levels of SDHB and UQCRC2 in tumor region (T) were higher than those in para-carcinoma (P) region in patients." (PMID 39856069, 2025). "Plasma succinate to fumarate ratios effectively distinguished tumor-bearing and asymptomatic patients with and without SDHx PV with promising diagnostic performance (areas under the receiver operating characteristic curve 0.86-0.95), although higher levels were noted in individuals with SDHB PV." (PMID 39145115, 2024). "This process also promotes the expression of succinate dehydrogenase complex iron sulfur subunit B (SDHB), thereby improving mitochondrial function and supporting tumor development." (PMID 38853203, 2024). "It is thought the rarity and low penetrance of SDHA-related tumours are due to the low frequency of LOH at 5p15, where SDHA is located, compared to the more common losses at 1p36 and 11q23 loci where SDHB and SDHD are located." (PMID 39133175, 2024). "Iron supplementation or ectopic expression of SDHB or ISC assembly 1 (ISCA1) can improve mitochondrial defects and promote tumour progression." (PMID 38853203, 2024). "The deleted regions contained the tumour suppressors CDKN2C, SDHB, and SFPQ in 1p and CDKN2A in 9p in metastatic samples and the tumour suppressors BCL10 and NOTCH2 and the oncogenes JAK1 and NRAS in 1p in the non‐metastatic sample group." (PMID 37622176, 2023). "Clinical data were extracted from medical records, and immunohistochemistry (IHC) for SDHB and SSTR2 was performed in patients with available tumor tissue." (PMID 36946182, 2023). "Three patients with metastatic PPGL (two with PV in SDHB and one with PV in NF1) died because of tumor progression." (PMID 37529773, 2023). "SDH deficiency is mainly caused by the biallelic inactivation of one of the four SDH subunit genes (SDHA, SDHB, SDHC, and SDHD) according to the classic tumor suppressor gene model." (PMID 36980917, 2023). "All three tumor types demonstrated enrichment of hypermethylation in the CpG island probes consistent with CIMP and SDHB-RCC showed the greatest enrichment (76.3%)." (PMID 36455002, 2022). "To clarify the correlation between 7 PRGs (BTK, CASP5, EEF2K, GZMA, NR1H2, RIPK3, and SDHB) derived from LASSO Cox regression analysis and immune infiltration in COAD, we applied Tumor Immune Estimation Resource (TIMER) database on these genes." (PMID 35912258, 2022).